MLKL (mixed lineage kinase domain like pseudokinase)
Diseases named in the same sentence as MLKL in open-access papers (continued):
Sharing a sentence is not in itself a finding about the gene and the disease.
breast carcinoma (continued). "To assess the susceptibility of MLKL-high TNBC cell lines to CNLs, we examined the effects of CNLs on the viability of breast cancer cell lines and measured IC50 values." (PMID 38474369, 2024). "Tumor necroptosis often happens in advanced solid tumors, and blocking necroptosis by MLKL deletion in breast cancer dramatically reduces tumor metastasis." (PMID 36703228, 2023). "To confirm the role of tumor necroptosis in breast cancer metastasis, we examined the effect of MLKL deletion on lung metastasis in the genetically engineered MMTV-PyMT spontaneous breast cancer model." (PMID 36703228, 2023). "Zinc oxide nanoparticles (ZnO-NP) significantly induce necroptosis by the upregulation of RIPK1, RIPK3, and MLKL expression in human MCF-7 breast cancer cells." (PMID 36361505, 2022). "The obtained data indicate that both breast cancer lines had some basal level of MLKL activation, which was observed by the detection of a phospho-MLKL band in the extracts from the control cultures." (PMID 35011734, 2022). "Knockout of the RIPK1, RIPK3, or MLKL genes in breast cancer cells significantly reduces the oncogenic activity of these cells and sensitizes the breast cancer cells to radiation therapy." (PMID 35965497, 2022). "Previous studies have found that necroptosis is prevalent in mouse breast cancer necrotic areas, and the phosphorylation level of mixed lineage kinase domain-like protein (MLKL) is significantly increased in late breast cancer." (PMID 36675706, 2022). "The results also showed that recent studies are increasingly focused on tumor regulation, with these keywords continuing until 2021, including membrane, breast cancer, protection, RIPK1, modulation, pseudokinase MLKL, deficiency, and cycle." (PMID 36204681, 2022). "In a mouse breast cancer model, the absence and depletion of MLKL blocked metastasis of breast cancer cells to the lung." (PMID 35330731, 2022). "It has been suggested that MLKL-mediated necroptosis in tumor cells promotes lung metastasis of breast cancer." (PMID 36675706, 2022). "RIPK1, RIPK3, and MLKL have been found to promote tumorigenesis in several breast cancer cell lines, and the suppression of these factors can significantly weaken the tumorigenicity and sensitize therapeutic response to radiotherapy." (PMID 33665167, 2020). "Notably, although the DS variant-dependent increase in cFLIP level was only transient in luminal breast cancer cells, it temporally correlated with the dynamic of the DS-induced activation of the necroptotic effector MLKL as previously observed in these cells." (PMID 41148796, 2025). "A clinical study of breast cancer tissue specimens showed that compared to adjacent non-cancerous tissues, the mRNA and protein expression levels of tumor necrosis factor alpha (TNFα), RIPK1, RIPK3, and MLKL were significantly elevated in breast cancer tissues." (PMID 41346619, 2025). "In concluding, it seems that the effect on adhesion receptors might play a fundamental role in the activation of MLKL and the induction of necroptosis that were triggered by high doses of DS in luminal breast cancer cells." (PMID 39062543, 2024). "Our present examinations together with our previous results indicated that at least certain structural variants of DS can significantly stimulate the activation of the necroptotic effector MLKL in various luminal breast cancer cell lines, including both the primary tumor and metastatic cells." (PMID 39062543, 2024). "Similarly, among the 50 breast cancer cell lines examined, MLKL expression was higher in TNBC-classified cell lines." (PMID 38474369, 2024). "The downregulation of RIPK3 and MLKL may contribute to a poor prognosis in multiple cancers (such as breast cancer, melanoma, colorectal cancer and acute myeloid leukaemia)." (PMID 37580654, 2023).
breast carcinoma (continued). "On the one hand, the downregulation of RIPK3 or MLKL is related to poor prognosis of various types of cancer, such as breast cancer, colorectal cancer, acute myeloid leukemia, head and neck squamous cell carcinoma, melanoma, cervical squamous cell carcinoma, gastric cancer, and ovarian cancer." (PMID 34977874, 2021). "The expression of these genes was analyzed in the breast cancer cells that had been exposed to the variants for three hours because, after such an incubation period, the effects of these glycans on both the RIPK3 upregulation and MLKL activation were observed in our previous studies." (PMID 41148796, 2025). "High MLKL expression correlated positively with good prognosis in colorectal cancer, high-risk human papillomavirus (HR-HPV) cervical cancer, ovarian cancer, and pancreatic adenocarcinoma, but negatively with breast cancer, cervical squamous cell carcinoma, and gastric cancer." (PMID 38961535, 2024). "In turn, the role of the fine-grained phospho-MLKL in luminal breast cancer cells remains unclear." (PMID 39062543, 2024). "Despite their important roles in specific types of lytic cell death, at least in these unstratified breast cancer patients, NINJ1, GSDMD and MLKL showed much lower correlation with overall response to chemotherapy." (PMID 41225536, 2025). "To recapitulate the high expression of MLKL in TNBC, we investigated MLKL mRNA expression in breast cancer cell lines." (PMID 38474369, 2024). "The antifungal drug miconazole was reported to induce both apoptotic and necroptotic cell death in human MDA-MB-231 breast cancer cells via augmented Bax/Bcl-2 ratio, upregulation of RIPK3 and MLKL phosphorylation levels, and ROS generation." (PMID 36361505, 2022). "Our data also showed that ROS activated major necrosome complex cascade genes, such as RIPK, RIPK3, and MLKL, especially in YARS-overexpressing breast cancer cell lines." (PMID 33239070, 2020). "Consistent with this, various cancer cell lines, including the A549, HCC4006, H2009 (lung cancer cell lines) and MDA-MB231 (breast cancer cell line) cells, showed increased sensitization to TRAIL-induced cell death upon depletion of MLKL." (PMID 32917855, 2020). "MLKL expression is transcriptionally up-regulated by interferon-γ-regulatory factor 1 (IRF1) and the signal transducer and activator of transcription 1 (STAT1) in MDA-MB-231 breast cancer and HeLa cervical cancer cell lines." (PMID 38474369, 2024). "MLKL mRNA expression correlated with IRF1 and STAT1 mRNA expression, but not with ESR1 expression, in breast cancer cell lines." (PMID 38474369, 2024).
melanoma (31 papers, 2015 to 2025). A malignant, usually aggressive tumor composed of atypical, neoplastic melanocytes. "In line with our preclinical data, we found that high expression of MLKL was associated with prolonged overall survival in patients with malignant melanoma." (PMID 40345706, 2025). "Multivariable Cox regression identified low MLKL expression in melanoma samples as an independent risk factor for death (HR 0.51, 95% CI 0.38 to 0.69) when controlling for stage of disease (UICC tumor status), age, and gender." (PMID 40345706, 2025). "Taken together, these patient data corroborate our preclinical findings that high transcriptional activity of MLKL in melanoma tissue is associated with prolonged overall survival and durable response to ICI immunotherapy." (PMID 40345706, 2025). "Our findings from patients with malignant melanoma are in line with a previous meta-analysis associating low transcriptional activity of MLKL in tumor samples with unfavorable disease development in various forms of cancer." (PMID 40345706, 2025). "In humans, transcriptome analysis of melanoma samples revealed a strong association between high expression of MLKL and prolonged overall survival and durable clinical response to immunotherapy with anti-PD-1 and/or anti-CTLA-4 checkpoint inhibitors." (PMID 40345706, 2025). "We previously reported that transfection of mRNA encoding MLKL results in B16 melanoma cell death within 16 h after transfection." (PMID 31480289, 2019). "We next analyzed the extent and mode of cell death of B16 melanoma cells after transfection with mRNA encoding MLKL or tBid." (PMID 30143632, 2018). "Indeed, we found that loss of RIPK3 in melanoma cells phenocopied the ICI immunotherapy resistance of MLKL-deficient tumors." (PMID 40345706, 2025). "Also, for the clinically more relevant combination of anti-PD-1 and anti-CTLA-4, we found strongly reduced antitumor activity in mice bearing melanoma with genetic deficiency for MLKL." (PMID 40345706, 2025). "However, direct intramelanoma delivery of either the RIPK3 gene via adenovirus or mRNA encoding MLKL, a necroptosis executioner, elicited both necroptosis and potent antitumor immunity in melanoma model mice." (PMID 38336727, 2024). "In melanoma cells with active melanogenesis, the use of melanin synthesis inhibitors to induce depigmentation could also restore the susceptibility of melanoma cells to RIPK1/RIPK3/MLKL-mediated necroptosis." (PMID 35359389, 2022). "Finally, to provide further proof that successful mRNA transfections are not limited to the eGFP-mRNA used so far, we proceeded with the transfection of murine MLKL (mixed lineage kinase domain-like)-encoding mRNA in B16F10 murine melanoma cells." (PMID 34138203, 2020). "In adjacent tumor-draining lymph nodes of MLKL−/− melanomas, we found reduced abundance of cDC1s compared with wild-type tumors." (PMID 40345706, 2025). "Upon combined ICI immunotherapy treatment of mice bearing chimeric tumors, we observed similar tumor growth control of both wild-type and MLKL−/− melanomas." (PMID 40345706, 2025). "Although RIPK1 and MLKL levels are homogeneous in most melanoma cell lines, the expression of RIPK3 is extremely low, which has been associated with the absence of necroptosis." (PMID 40710498, 2025). "Lastly, vaccinia viruses (VACV) were utilized for the intratumoral delivery of MLKL protein in a B16 melanoma tumor model, resulting in potent anti-tumor activity." (PMID 40691738, 2025). "Therapeutic inhibition of CTLA-4, which aims to invigorate de novo priming and expansion of tumor-specific T cells was indeed less efficient in mice bearing MLKL−/− melanomas." (PMID 40345706, 2025). "Gene set enrichment analysis of differentially expressed genes between patients with melanoma with high or low MLKL expression showed that many of the upregulated genes in MLKLhigh tumors clustered in inflammation-related pathways." (PMID 40345706, 2025).
melanoma (continued). "The murine oral squamous cell carcinoma cell line MOC1 showed particularly high in vivo responsiveness to ICI immunotherapy, which similarly to B16 melanoma was completely dependent on tumor cell-intrinsic MLKL activity." (PMID 40345706, 2025). "In the first method, MLKL mRNA was delivered into melanoma and colon carcinoma tumors using electroporation, combined with the immune checkpoint inhibitor blocker, anti-PD1." (PMID 40691738, 2025). "Secondly, exogenous recombinant MLKL protein was delivered into murine B16 melanoma tumor cells using laser-induced vapor nanobubble (VNB) photoporation." (PMID 40691738, 2025). "Through LASSO regression, the following six genes were specifically identified to have an irreplaceable prognostic effect on melanoma patients: MLKL, PARVA, PKP1, PSME1, RNF114, and TROAP." (PMID 37127623, 2023). "NRIR, firstly found to be associated with melanoma by our study, was positively correlated with CYLD, MLKL, STAT1, and TNFSF10." (PMID 37147395, 2023). "Reconstituting RIPK3 can reactivate the RIPK1/RIPK3/MLKL signaling pathway, which can eventually overcome the resistance of melanoma to necroptosis." (PMID 37580654, 2023). "For example, intra-tumoral delivery of MLKL mRNA in mice delays the growth of primary B16 melanoma tumors due to necroptotic cell death and consequent activation of the immune system to attack tumor neo-antigens." (PMID 35422482, 2022). "In melanoma, selective inhibition of the RIPK3/MLKL axis by loss of RIPK3 is essential to prevent necroptosis." (PMID 35610275, 2022). "This study investigates the role of MLKL during melanoma initiation and progression using a tamoxifen-inducible melanoma mouse model driven by melanocyte-specific overexpression of mutated Braf and simultaneous deletion of Pten (BrafV600EPten−/−)." (PMID 35422482, 2022). "Unraveling the possible duality of MLKL in melanoma and its cell death resistance mechanisms will contribute to the development of potential therapies beyond necroptosis." (PMID 35422482, 2022). "Pre-treatment with 5-AD (a demethylating agent) increases the expression of MLKL and the activation of necroptosis in melanoma cell lines." (PMID 35748782, 2022). "In melanoma cells with active melanogenesis, induction of depigmentation with a melanin synthesis inhibitor restores melanoma cell sensitivity to RIPK1/RIPK3/MLKL-mediated necroptosis." (PMID 35610275, 2022). "Overall, our results indicate that in this genetic model MLKL has a minor role during melanoma initiation and progression." (PMID 35422482, 2022). "To the best of our knowledge, we are the first to demonstrate that CV extract can induce RIPK1/RIPK3/MLKL-mediated necroptosis in depigmented melanoma cells." (PMID 34072104, 2021). "Related to the mechanism of action, our results show that CV extract induce RIPK1/RIPK3/MLKL-dependent necroptosis, in the depigmented melanoma cells, which serves as an alternative mode of programmed cell death to eradicate apoptosis-resistant cancer cells." (PMID 34072104, 2021). "Both UVB and UVC have also been shown to increase MLKL protein level, and vapor nanobubble photoporation-mediated delivery of MLKL protein to melanoma cells effectively induced necroptosis." (PMID 32340261, 2020). "Several previous studies demonstrated that dabrafenib actually inhibits the RIPK3-mediated phosphorylation of MLKL in vitro using human melanoma cells, human dermal fibroblasts, human colon cancer cells, and leukemia cells." (PMID 31817643, 2019). "We compared the antitumor effect of the MLKL-mRNA treatment approach with repeated injections of dox in the B16 melanoma model." (PMID 30143632, 2018). "Our findings indicate that MLKL exhibits a clear anti-tumor effect in melanoma." (PMID 39439891, 2024). "However, the specific regulatory pathways of USP30-AS1 interfering with RIPK3 and MLKL in melanoma still need further investigation." (PMID 37147395, 2023).
melanoma (continued). "Currently, we cannot conclude whether MLKL directly contributes to melanoma dissemination in our model, even though numerous reports established its role in metastasis of various solid tumors." (PMID 35422482, 2022). "RIPK1, RIPK3, and MLKL might have different necroptosis-(in)-dependent roles during melanoma development." (PMID 35422482, 2022). "Dabrafenib disrupted RIPK3 and MLKL interactions that was associated with decreased levels of MLKL phosphorylated at Ser358, and prevented from induction of necroptosis in RIPK3-expressing melanoma cells." (PMID 32340261, 2020). "Finally, to assess the extent of cell death in vivo, B16 melanoma cells were injected subcutaneously (s.c.)into the flank of C57Bl/6 mice, and 6 days later, MLKL- and tBid-mRNA was administered into the tumor (mRNA injection followed by electroporation)." (PMID 30143632, 2018). "Cell death induced by mRNA encoding tBid or MLKL did not activate nuclear factor (NF)-κB signaling in the B16 melanoma cells." (PMID 30143632, 2018). "Therefore, we assessed whether defects in MLKL-mediated necroptosis in tumor cells impacted DC functionality and the formation of ICI-enhanced antitumor T-cell responses, using our established model of MLKL−/− B16 melanoma-bearing mice." (PMID 40345706, 2025). "Furthermore, intratumor MLKL-mRNA delivery synergizes with immune-checkpoint blockades (ICBs), impedes lymphoma growth in mice, and improves anti-tumor activity in syngeneic mice with colon carcinoma and melanomas." (PMID 36361505, 2022). "Necroptosis, governed by the receptor-interacting protein kinase 1 (RIPK1)/RIPK3 mixed lineage kinase domain-like protein (MLKL) signaling axis, can synergize with immunotherapy to enhance anti-melanoma immune responses when activated." (PMID 40497999, 2025). "A dose-dependent increase in p-MLKL and p-RIP was observed following RSV treatment in both melanoma cell lines; however, the magnitude of induction was notably higher in G361 cells." (PMID 41614770, 2025). "Further studies revealed that in amelanotic melanoma cells, PBPs-induced death is related to inducing the RIPK1/RIPK3/MLKL-mediated necroptosis." (PMID 35359389, 2022). "In another study, pretreatment with BAY 87-2243, a specific inhibitor of mitochondria complex-I, triggered ROS generation, mitochondrial dysfunction and mitophagy, following RIPK3/MLKL activation and induction of necroptosis in BRAFV600E melanoma cells." (PMID 36361505, 2022). "We found that ZBP1 knockdown leads to the reduction of tumor necrosis and MLKL phosphorylation, but increases of cleaved Casp-3 and TUNEL positive cells in B16 melanoma tumors." (PMID 33976222, 2021). "We co-cultured CV-stimulated depigmented melanoma cells with selected kinases inhibitors: necrostatin-1 (Nec-1), GSK’872 and necrosufonamide (NSA), which specifically target RIPK1, RIPK3, and MLKL activity, respectively." (PMID 34072104, 2021). "For necroptosis, decreased RIP1/RIP3/MLKL expression has been found in AML, melanoma, and breast, colorectal, gastric, ovarian, head and neck squamous cell, and cervical squamous cell carcinomas." (PMID 33467668, 2021). "In this study, we show that caspase-3 or -8, or MLKL protein delivery by VNB photoporation induces, respectively, apoptotic and necroptotic cell death in murine B16 melanoma tumor cells." (PMID 31480289, 2019). "MLKL and RIPK1 protein was present in most melanoma cell lines, nevus cells, and primary melanocytes." (PMID 26355347, 2015). "In mice bearing melanomas without functional MLKL-mediated necroptosis signaling, ICI immunotherapy failed to boost activation and cytolytic function of CD8+ tumor-infiltrating T cells and had reduced effects on CD4+ T cell activation." (PMID 40345706, 2025). "While combined ICI immunotherapy in mice bearing wild-type melanomas potently enhanced the frequency of circulating tumor model antigen OVA-specific CD8+ T cells, this therapy-induced beneficial effect was largely abrogated in mice bearing MLKL−/− tumors." (PMID 40345706, 2025).